OR9Q1 (olfactory receptor family 9 subfamily Q member 1)
Description:
Odorant receptor.
Tractability: Antibody: UniProt places it where antibodies can reach, with medium confidence; UniProt predicts a signal peptide or a membrane-spanning region; its Gene Ontology location is reachable by antibodies, with medium confidence.
Gene: Protein-coding gene on chromosome 11 (58,023,881 to 58,181,616, forward strand). Ensembl gene ENSG00000186509.
Subcellular location: Cell membrane
Pathways (Reactome):
Sensory Perception: Expression and translocation of olfactory receptors
Gene Ontology:
Molecular function: olfactory receptor activity; G protein-coupled receptor activity
Biological process: G protein-coupled receptor signaling pathway; sensory perception of smell; detection of chemical stimulus involved in sensory perception of smell
Cellular component: plasma membrane; membrane
Genetic constraint (gnomAD): Loss-of-function variants: 3 observed, 5.82 expected, observed/expected ratio (o/e) 0.52, 90% interval 0.23 to 1.32. That is too few expected variants to judge how well the gene tolerates losing a copy. Missense variants: 374 observed, 398.1 expected, observed/expected ratio (o/e) 0.94, 90% interval 0.86 to 1.02. Synonymous variants: 152 observed, 155.66 expected, observed/expected ratio (o/e) 0.98, 90% interval 0.86 to 1.12.
Homologues: Orthologues: chimpanzee OR9Q1 (95% identical), macaque OR9Q1 (92% identical), mouse Or9q1 (82% identical), pig OR9Q1 (82% identical), rat Or9q1 (82% identical), rabbit OR9Q1 (79% identical), dog OR9Q4 (69% identical). Paralogues in human: OR9Q2 (73% identical), OR9I1 (56% identical), OR5B21 (50% identical), OR5B12 (48% identical), OR5A1 (47% identical), OR8A1 (47% identical), OR8D4 (47% identical), OR5AP2 (47% identical), OR8G1 (46% identical), OR8G5 (46% identical), OR8U3 (46% identical), OR5AR1 (46% identical), and 84 more.
Diseases named in the same sentence as OR9Q1 in open-access papers:
OR9Q1 is named in the same sentence as 2 diseases in open-access papers, as found by Europe PMC text mining. Sharing a sentence is not in itself a finding about the gene and the disease. The quoted sentences say what the papers report.
cancer (1 paper, 2016). A tumor composed of atypical neoplastic, often pleomorphic cells that invade other tissues. "Some of them are cancer related, such as POU2F3, NKD1 and CYP2C8, while LINC00189, GCC2 and OR9Q1 genes are rarely reported in human diseases." (PMID 27602771, 2016).
OR9Q1 also shares sentences with these, for which no sentence is quoted: squamous cell carcinoma of urinary bladder (1 paper).